MEX3A (mex-3 RNA binding family member A)
Diseases named in the same sentence as MEX3A in open-access papers (continued):
Sharing a sentence is not in itself a finding about the gene and the disease.
glioblastoma (11 papers, 2020 to 2025). The most malignant astrocytic tumor (WHO grade IV). "This study analyzes the correlation between MEX3A expression and clinical-molecular features, assessing its diagnostic, prognostic, and therapeutic value in glioblastoma (GB), the most aggressive glioma subtype." (PMID 40958871, 2025). "MEX3A, an RNA-binding ubiquitin ligase, has been verified to be involved in glioblastoma multiforme initiation and progression." (PMID 37180696, 2023). "RNA-binding ubiquitin ligase MEX3A promotes the progression of glioblastoma by inducing the ubiquitination and degradation of RIG-1." (PMID 34486491, 2021). "In glioblastoma cells, MEX3A interacts with the tumor suppressor RIG-I inducing its ubiquitinylation and the proteasome-dependent degradation, supporting tumor growth." (PMID 33072742, 2020). "MEX3A is overexpressed in pancreatic ductal adenocarcinoma and strongly up-regulated in glioblastoma samples." (PMID 33072742, 2020). "Notably, a similar mechanism of tumorigenesis regulation via ubiquitylation has been reported for MEX3A in glioblastoma." (PMID 38424632, 2024). "It was reported that the tumorigenesis of human glioblastoma may be affected by Mex3A-induced ubiquitylation and degradation of RIG-I." (PMID 35865536, 2022). "They mediate ubiquitination, leading to a proteasome-dependent degradation of their target proteins, also including cancer-relevant target proteins like the tumor suppressor RIG-I, which could be ubiquitinated by MEX-3A, during glioblastoma tumorigenesis." (PMID 32717840, 2020). "Additionally, Mex3A seems to have an important role as post-translational regulators also acting as E3 ubiquitin ligase in glioblastoma cells." (PMID 33072742, 2020). "Recent data showed that MEX3A is up-regulated in glioblastoma specimens." (PMID 33072742, 2020). "This recent study demonstrated that MEX3A induces the ubiquitylation and proteasomal degradation of the tumor suppressor RIG-I in glioblastoma, resulting in increased cell growth." (PMID 38424632, 2024). "For example, MEX-3A and MEX-3C ubiquitinate the tumor suppressor RIG-I, which affects tumorigenesis in glioblastoma." (PMID 32717840, 2020). "The RNA-binding ubiquitin ligase MEX3A is overexpressed in glioblastoma multiforme specimens, and it targets retinoic acid inducible gene-I (RIG-I) for ubiquitylation and degradation to alter the tumorigenesis of glioblastoma multiforme." (PMID 33997099, 2021).
liver cancer (9 papers, 2020 to 2024). An epithelial or non-epithelial malignant neoplasm that arises from the liver. "The high mRNA expression of pescadillo (PES1), high mobility group A2 (HMGA2), microtubule-associated serine and threonine kinase 2 (MAST2), trophinin-associated protein (TROAP), and MEX3A was associated with poor prognosis for liver cancer." (PMID 32420386, 2020). "In summary, this is the first study to report the association between MEX3A mRNA and the clinical characteristics and survival of liver cancer patients." (PMID 31998552, 2020). "ROC curve analysis showed that MEX3A had moderate diagnostic ability in patients with liver cancer (AUC=0.837)." (PMID 31998552, 2020). "This is the first study to investigate the expression of MEX3A mRNA in liver cancer, revealing its association with specific clinical features." (PMID 31998552, 2020). "Through Univariate and Multivariate Cox analysis of OS, MEX3A (HR = 2.26, 95% CI [1.58–3.23], p < 0.0001) was identified as an independent risk factor for the prognosis of liver cancer along with T stage (p < 0.0001) and residual tumors (p = 0.026)." (PMID 31998552, 2020). "Moreover, it has been established that Mex3a promoter methylation, operating as an independent and potent factor in the development of liver cancer, evinces an inverse association with Mex3a mRNA levels." (PMID 39564121, 2024). "Furthermore, increased MEX3A levels were also reported in liver cancer and were shown to be significantly associated with worse patient survival." (PMID 36507941, 2023). "Moreover, a higher level of MEX3A was significantly associated with shorter survival of patients with liver cancer." (PMID 33997099, 2021). "Furthermore, increased MEX-3A levels are also reported in liver cancer, which were significantly associated with a poor patients’ survival." (PMID 32717840, 2020). "Association between MEX3A expression and clinical characteristics in liver cancer patients." (PMID 31998552, 2020). "MEX3A showed moderate diagnostic ability for liver cancer (AUC = 0.837)." (PMID 31998552, 2020). "The Mex3a promoter methylation levels and mRNA levels were also independent factors in the development of liver cancer." (PMID 39564121, 2024). "The presence of Mex3a promoter hypomethylation in hepatocellular carcinoma can be used as a non-invasive biomarker for the early detection of liver cancer." (PMID 39564121, 2024). "Of note, upon assessment of each sub-variable group, Kaplan–Meier curves revealed that the liver cancer patients with high MEX3A expression had a poor OS." (PMID 31998552, 2020). "Univariate and Multivariate Cox analysis suggested that MEX3A (HR = 2.19, 95% CI [1.54–3.12], p < 0.0001) was an independent risk factor to evaluate the RFS for liver cancer along with T stage (p < 0.0001) and residual tumor status (p = 0.024)." (PMID 31998552, 2020). "Area under the ROC curves was 0.837, which provided evidence that MEX3A was a potential biomarker for liver cancer diagnosis." (PMID 31998552, 2020). "We further investigated the potential of MEX3A as an independent predictor of liver cancer prognosis." (PMID 31998552, 2020). "The aim of this study was to explore the clinicopathological characteristics and prognostic significance of MEX3A mRNA expression in liver cancer." (PMID 31998552, 2020). "In this study, we analyzed the expression of MEX3A in liver cancer and assessed its clinicopathological potential." (PMID 31998552, 2020). "Relationship between clinical parameters, MEX3A mRNA expression and overall survival in liver cancer patients." (PMID 31998552, 2020). "Further clinicopathological information and corresponding clinical tissue samples should be obtained to further validate these findings and to establish MEX3A as a novel prognostic for patients with liver cancer." (PMID 31998552, 2020). "Combined with our findings, the role of MEX3A in cancer progression explains its clinical links to poor histological grade and poor patient prognosis in liver cancer." (PMID 31998552, 2020).
liver cancer (continued). "Relationship between clinical parameters, MEX3A mRNA expression and relapse-free survival in liver cancer patients." (PMID 31998552, 2020). "We found that MEX3A was up-regulated in liver cancer which increased according to histological grade (p < 0.001)." (PMID 31998552, 2020). "In liver cancer, MEX3A mRNA expression level was significantly up-regulated compared to normal tissues (p = 1.1e−14) and increased with higher histological grades (p = 0.00016)." (PMID 31998552, 2020). "Future studies should explore the mechanisms by which MEX3A promotes liver cancer in vivo and in vitro." (PMID 31998552, 2020). "In mammals, Mex3A is upregulated in liver cancer and used as the prognostic factor of liver cancer." (PMID 35865536, 2022). "MEX3A mRNA expression and clinical characteristics in liver cancer patients." (PMID 31998552, 2020). "Moreover, our results indicate that MEX3A plays a significant role in the prognosis of liver cancer and can be used as an independent factor to predict liver cancer progression." (PMID 31998552, 2020). "MEX3A has great potential to predict the prognosis of liver cancer patients." (PMID 31998552, 2020). "In this study, MEX3A mRNA was identified as overexpressed in liver cancer tissue and could effectively evaluate the prognosis of liver cancer patients as an independent predictor." (PMID 31998552, 2020). "MEX3A expression shows promise as an independent predictor of liver cancer prognosis." (PMID 31998552, 2020). "Moreover, MEX3A was identified as an independent prognostic factor of liver cancer (p < 0.001)." (PMID 31998552, 2020). "Second, this study did not explore Mex3a promoter methylation in the context of other pathogens or liver cancer, such as HCV infection, alcohol-related liver disease, or non-alcoholic fatty liver disease." (PMID 39564121, 2024). "In this study, based on a considerable previous effort about the relationship between Mex3a levels and liver cancer development, we propose that a more effective strategy for detecting HCC is the combined test of AFP, Mex3a mRNA levels, and Mex3a promoter methylation levels." (PMID 39564121, 2024). "A total of 423 tissue samples with MEX3A mRNA expression data, including 373 liver cancer and 50 normal liver tissues were obtained from the TCGA." (PMID 31998552, 2020).
pancreatic ductal adenocarcinoma (9 papers, 2020 to 2023). An infiltrating adenocarcinoma that arises from the epithelial cells of the pancreas. "In pancreatic ductal adenocarcinoma, MEX3A expression is significantly up-regulated which is linked with advanced stage of pancreatic ductal adenocarcinoma." (PMID 34486491, 2021). "MEX3A was overexpressed, and MEX3A knockdown suppressed the proliferation of pancreatic ductal adenocarcinoma cells." (PMID 35715407, 2022). "However, the downregulation of MEX3A can inhibit the growth of pancreatic ductal adenocarcinoma in vivo and in vitro." (PMID 34486491, 2021). "Notably, downregulation of MEX3A inhibited cell growth and migration and promoted apoptosis in pancreatic ductal adenocarcinoma." (PMID 33997099, 2021).
bladder cancer (8 papers, 2017 to 2023). "In this study, we did a thorough search for novel fusion transcripts in bladder cancer using RNA sequencing and sought to determine the effect of mex3a expression on the overall survival of BLCA." (PMID 28903380, 2017). "Mex-3A protein was detected in bladder carcinoma sections with a mean staining intensity of 7.06±2.60." (PMID 28977858, 2017). "Considerable research efforts showed that the downregulation of MEX3A in bladder cancer could inhibit the proliferation of cells, promote cell apoptosis, thereby exerting a therapeutic effect to inhibit the further deterioration of bladder cancer cells." (PMID 33414423, 2021).
colon carcinoma (8 papers, 2017 to 2025). "Compared to control, expression levels of Klf4 significantly increased in AOM-DSS-induced colon tumors from cKO mice, while MEX3A overexpression in NCM460 cells downregulated KLF4 protein and restricted its nuclear localization." (PMID 36276637, 2022). "We found that MEX3A high expression in colon cancer tissue than normal tissue." (PMID 38914858, 2024). "Similarly, analysis of 66 colon adenocarcinoma/adjacent normal tissue pairs from individual patients from our cohort revealed consistent overexpression of MEX3A in colon tumors." (PMID 36276637, 2022). "Collectivelly, these findings demonstrate that MEX3A activates WNT signaling in colon cancer." (PMID 36276637, 2022). "Next, we investigated whether MEX3A regulates stemness of colon tumor cells." (PMID 36276637, 2022). "Analogous to Mex3a, E2f3 is also dramatically upregulated in AOM-DSS-induced mouse colon tumors, and is highly expressed in ISCs and in regenerative foci following irradiation." (PMID 36276637, 2022). "Further supporting the pro-oncogenic function of MEX3A, in vitro data showed that its overexpression promotes proliferation in HCT116 human colon cancer cell line, and shifted relative cell cycle phase distribution toward S phase." (PMID 36276637, 2022). "Ten RNAs were finally obtained related to colon cancer, which were hsa-miR-2682-5p, hsa-miR-1277-3p, ANGPTL1, SLC22A18AS, FENDRR, PHLPP2, hsa-miR-302a-5p, APCDD1, MEX3A and hsa-miR-509-3-5p." (PMID 36101384, 2022). "In line with this, MEX3A upstream regulator E2F3 also functions as an oncogenic transcription factor in a variety of cancers 41-43, and high E2F3 levels confer poor overall survival and disease-free survival in patients with colon cancer." (PMID 36276637, 2022). "In colon cancer, most likely because of the lack of data, cross-correlation identified only three correlating groups (EIF4E3/MEX3A, SSR1/RPL39L, and PPARGC1B/CDKN2A)." (PMID 39940786, 2025).
glioma (8 papers, 2021 to 2026). A benign or malignant brain and spinal cord tumor that arises from glial cells (astrocytes, oligodendrocytes, ependymal cells). "Overall, our findings align with the growing body of research identifying biomarkers with diagnostic and prognostic significance in gliomas, further reinforcing the relevance of MEX3A in this context." (PMID 40958871, 2025). "In this regard, we discovered MEX3A as a new diagnostic and independent prognostic biomarker for GB making promising advancement in the field of glioma research." (PMID 40958871, 2025). "Elevated MEX3A expression associates with more severe clinicopathological and molecular features of glioma patients." (PMID 40958871, 2025). "We investigated the putative association between mRNA expression levels of MEX3A and several clinicopathological and molecular characteristics of glioma patients." (PMID 40958871, 2025). "On the contrary, lower levels of MEX3A were observed in IDH1 mutated gliomas." (PMID 40958871, 2025). "Although the relationship between MEX3A and several types of malignant tumors has been revealed, its association with glioma is still unknown." (PMID 33414423, 2021). "Recently, it has been demonstrated that high expression of Muscle Excess 3A (MEX3A) correlates with poor overall survival (OS) in gliomas, generating interest in its potential as a biomarker and therapeutic target." (PMID 40958871, 2025). "Although the involvement of MEX3A in glioma pathogenesis and resistance to treatments has previously been explored, its clinical relevance deserves further investigations." (PMID 40958871, 2025). "Correlation between MEX3A mRNA expression and clinical and molecular characteristics of glioma patients." (PMID 40958871, 2025). "In glioma, MEX3A upregulates CCL2, a chemokine known to support proliferation, angiogenesis, and immune evasion, leading to alteration of the tumor microenvironment (TME) and promoting tumorigenesis." (PMID 40958871, 2025). "Firstly, MEX3A is highly expressed across all subtypes of gliomas, providing a reliable indicator of disease presence and progression." (PMID 40958871, 2025). "In this study, they showed that blocking MEX3A makes GB cells more sensitive to treatment by restoring MMR function.These findings, highlight the need to fully elucidate the role of MEX3A in glioma pathogenesis." (PMID 40958871, 2025). "The last ranked mRNA, MEX3A, is a promoter for glioma and a therapeutic target in the treatment of glioma." (PMID 36101384, 2022). "Regarding the current study, the generally higher MEX3A expression was detected in glioma tissues compared with that in normal tissues, which was also verified by the data mining of TCGA." (PMID 33414423, 2021). "The mechanistic research of this study revealed CCL2 as a potential downstream target of MEX3A in the regulation of glioma." (PMID 33414423, 2021). "Overall, MEX3A was identified as a potential tumor promoter in glioma development and therapeutic target in glioma treatment." (PMID 33414423, 2021). "Subsequently, the potential role of MEX3A in glioma was validated by the in vitro experiments in which MEX3A knockdown inhibited glioma cell proliferation and motility, and promoted glioma cell apoptosis." (PMID 33414423, 2021). "Altogether, the results demonstrated that CCL2 not only has a co-expression profile with MEX3A but also possesses similar regulatory effects on glioma with MEX3A." (PMID 33414423, 2021). "In this study, we explored the clinical significance of MEX3A in glioma through immunohistochemistry (IHC) and statistical analysis." (PMID 33414423, 2021). "Conclusively, our study demonstrated the role played by MEX3A in glioma that MEX3A was a glioma tumor promotor." (PMID 33414423, 2021). "It was clarified that glioma tissues expressed a higher level of MEX3A in comparison with normal tissues." (PMID 33414423, 2021).